SLC27A5 (solute carrier family 27 member 5)
Diseases named in the same sentence as SLC27A5 in open-access papers (continued):
Sharing a sentence is not in itself a finding about the gene and the disease.
tumor (23 papers, 2013 to 2025). "SLC27A5 is a liver-enriched gene implicated in fatty acid and RNA metabolism, and its downregulation is associated with hepatic fibrosis, tumor aggressiveness, and recurrence." (PMID 41228357, 2025). "And low expression of SLC27A5 in tumor tissues was significantly associated with poor OS in patients with HCC." (PMID 35203444, 2022). "According to their study, SLC27A5 deficiency promotes tumor proliferation and chemoresistance by increasing 4-HNE level and consequently activating KEAP1/NRF2/TXNRD1 pathway." (PMID 33731144, 2021). "In addition, the solute carrier family 27 member 5 gene (SLC27A5) is associated with FAs uptake into cells and bile acid metabolism, while exerting a tumor-suppressive effect by suppressing TXNRD1 expression via the KEAP1/NRF2 pathway in HCC." (PMID 38833109, 2024). "So we supposed that SLC27A5 downregulation in tumor tissues might be associated with cancer metastasis." (PMID 33731144, 2021). "Meanwhile, we also observed that SLC27A5 depletion markedly enhanced the tumor-forming capacity in HepG2 and SNU449 cells, which was rescued by the re-expression of METTL14-US." (PMID 40290127, 2025). "To further investigate in vivo, we performed a limiting dilution assay to assess the tumor-initiating ability of SLC27A5-KO HepG2 cells stably transfected with METTL14-US." (PMID 40290127, 2025). "Functionally, SLC27A5 deficiency leads to increased lipid peroxidation, activating the NRF2/TXNRD1 pathway, which contributes to tumour progression and resistance to therapies like sorafenib." (PMID 41154605, 2025). "Collectively, these data supported that SLC27A5 deficiency facilitates the expression of PABPC1 and short 3'UTR isoforms of METTL14, thereby inhibiting METTL14 expression and promoting tumor progression." (PMID 40290127, 2025). "AAV‐mediated restoration of hepatic SLC27A5 decreased the liver weight and tumor numbers in Slc27a5−/‐ mice." (PMID 38059827, 2024). "In males, the expression of SLC27A5 was lower in the glioblastoma tumor (in the enhancing tumor region p = 0.05 and in the tumor core p = 0.01) compared to the peritumoral area." (PMID 37239243, 2023). "A negative correlation was also found between the expression of SLC27A5 and patient weight in the tumor core." (PMID 37239243, 2023). "In females, the expression of SLC27A5 was higher in the tumor core compared to the enhancing tumor region (p = 0.019)." (PMID 37239243, 2023). "Silencing of SLC27A5 promotes tumor progression by antioxidant and oncogenic signaling pathways and is associated with poor prognosis." (PMID 36635256, 2023). "Our previous work has shown that SLC27A5, inactivated by promoter hypermethylation, is a tumor suppressor gene in HCC." (PMID 36635256, 2023). "There was also a negative correlation between SLC27A3 expression in the enhancing tumor region and SLC27A5 in the peritumoral area." (PMID 37239243, 2023). "SLC27A5 participates in fatty acid transport and bile acid metabolism and functions as a tumor suppressor in HCC." (PMID 35898502, 2022). "SLC27A5 acts as a tumor suppressor and has anti-proliferative and anti-migratory abilities in HCC cells." (PMID 36421714, 2022). "SLC27A5 has been reported to participate in the transport of fatty acids, in the metabolism of bile acids, and to act as a tumor suppressor in HCC progression." (PMID 33834191, 2021). "GSEA analysis and in vitro assays suggested that SLC27A5 downregulation promoted tumor cell migration via enhancing epithelial-mesenchymal transition." (PMID 33731144, 2021). "The results showed that the top genes positively associated with PC1 included RBP4, SLC27A5, and PCK2, all of which were known tumor-related genes and correlated with cancer patients’ survival." (PMID 32231683, 2020). "Moreover, PIP4K2A‐S knockdown significantly inhibited hepatocarcinogenesis and lung metastasis in nude mice bearing SLC27A5‐KO tumor xenografts." (PMID 38059827, 2024).
tumor (continued). "Additionally, the expression of SLC27A5 in the tumor core was higher in females than in males (p = 0.00003)." (PMID 37239243, 2023). "However, the expression of SLC27A5 in the tumor core was lower than in the enhancing tumor region (p = 0.04)." (PMID 37239243, 2023). "In addition, we found that the insecticide diazinon increases the expression of SLC27A5, so diazinon has a potential anti-tumor effect on HCC." (PMID 35203444, 2022). "Collectively, our results implicate SLC27A5 and tyrosine-metabolizing enzymes as acting as tumor suppressor in HCC and coordinating lipid and tyrosine metabolism, which may be potential targets in HCC treatment." (PMID 35203444, 2022). "Spatial distribution of taurine metabolic genes (SLC27A5, CAV1) revealed pronounced heterogeneity, with tumor core regions exhibiting hyperactivation of taurine metabolism." (PMID 40630945, 2025). "In women, there was a positive correlation between ELOVL1 expression and SLC27A, SLC27A5, and SLC27A6 expression in the tumor core." (PMID 37239243, 2023). "Negative correlations were observed between SLC27A3 and SLC27A4 in the enhancing tumor region and between SLC27A1 and SLC27A5 in the tumor core." (PMID 37239243, 2023). "Positive correlations were observed between SLC27A4 and SLC27A5, SLC27A4 and SLC27A6, and SLC27A5 and SLC27A6 in all three tumor regions." (PMID 37239243, 2023). "In women, a positive correlation was observed between the expression of ELOVL1 and SLC27A4, SLC27A5, and SLC27A6 in the tumor core." (PMID 37239243, 2023). "Women also showed a negative correlation in the expression of SLC27A3 in the peritumoral area with the expression of SLC27A4, SLC27A5, and SLC27A6 in the enhancing tumor region." (PMID 37239243, 2023). "ARID3B, CXCR1, GATS, Itga6, Shh, SLC27A5, STC2, and VEGF play an important role in cell proliferation and tumor progression or metastasis." (PMID 35875133, 2022). "The results showed that SLC27A1 and SLC27A3 were higher-expressed in tumor samples of both sets, while SLC27A2, SLC27A4, and SLC27A5 expressions were much lower." (PMID 35927229, 2022). "We selected SLC27A5 as a prognostic gene of HCC and further in vitro assays suggested that it promoted tumor migration via enhancing EMT." (PMID 33731144, 2021). "Tumor samples of GSE14520 were divided into low expression and high expression subgroups according to the median expression level of SLC27A5." (PMID 33731144, 2021). "SLC27A5 was positively correlated with prognosis of HCC and was downregulated in tumor tissues compared with non-tumor tissues." (PMID 33731144, 2021). "Additionally, spatial transcriptomic analysis identified heterogeneous overexpression of core taurine metabolic genes (e.g., SLC27A5, CAV1) in tumor core regions, which were significantly co-localized with fibroblasts and macrophages." (PMID 40630945, 2025). "This is an unrecognized noncanonical mechanism for SLC27A5 to inhibit tumor progression independently of its enzymatic activity." (PMID 38059827, 2024). "A negative correlation was found between SLC27A1 in the peritumoral area and SLC27A6 in the tumor core, between SLC27A3 in the enhancing tumor region and SLC27A5 and SLC27A6 in the tumor core, and between SLC27A3 in the tumor core and SLC27A5 in the peritumoral area." (PMID 37239243, 2023). "Specifically, a positive correlation was observed between SLC27A3 and age in the enhancing tumor region, and a negative correlation was observed with SLC27A5." (PMID 37239243, 2023). "In the tumor core of women, there was a negative correlation between the expression of SLC27A5 and a positive correlation between the expression of SLC27A4 and SLC27A1 with age." (PMID 37239243, 2023). "Additionally, there was a positive correlation between SLC27A5 expression in the tumor core and SLC27A6 expression in the peritumoral area and between SLC27A5 expression in the peritumoral area and SLC27A6 expression in the tumor core." (PMID 37239243, 2023).
tumor (continued). "Specifically, a positive correlation was found between SLC27A1 and SLC27A4 with age in the tumor core, while a negative correlation was found with SLC27A5." (PMID 37239243, 2023). "In the tumor core, a negative correlation was found between the expression of SLC27A5 and BMI." (PMID 37239243, 2023). "Additionally, a negative correlation was found between SLC27A5 expression in the tumor core and BMI." (PMID 37239243, 2023). "In men, there was a negative correlation between the expression of SLC27A5 and a positive correlation between the expression of SLC27A3 with age in the enhancing tumor region." (PMID 37239243, 2023). "A positive correlation was observed between the expression of SLC27A1 and SLC27A3 in the enhancing tumor region, while a negative correlation was found with the expression of SLC27A4, SLC27A5, and SLC27A6." (PMID 37239243, 2023).
cancer (16 papers, 2017 to 2025). A tumor composed of atypical neoplastic, often pleomorphic cells that invade other tissues. "While little is known about the role of SLC27A5 in cancer, these mutations may be relevant in the light of the established importance of lipid metabolism dysregulation in cancer." (PMID 40359938, 2025). "The discovery of the SLC27A5-PABPC1-METTL14 axis deepens our understanding of the metabolic network of cancer and mRNA alternative polyadenylation." (PMID 40290127, 2025). "Further, analysis of the Cancer Dependency Map Portal (DepMap) revealed that SLC27A5 exhibited a significant co-dependency with FDX1 (r = 0.19, p = 1.7e-10)." (PMID 38157255, 2023). "Therefore, the SLC27A5 and tyrosine-metabolizing enzymes that we have identified coordinate lipid and tyrosine metabolism, regulate the cell cycle, and are potential targets for cancer treatment." (PMID 35203444, 2022). "For example, SLC27A5 is downregulated in HCC, enhancing sora-induced ferroptosis by inhibiting the NRF2/GSR pathway in cancer cells, presenting a potential therapeutic approach to overcome sora resistance." (PMID 39548421, 2024). "In summary, this study revealed a previously unknown moonlighting function of SLC27A5 in regulating APA to suppress HCC stemness, highlighting a potential link between metabolic enzymes and mRNA post-transcriptional processing in cancer." (PMID 40290127, 2025).
SLC27A5 also shares sentences with these, for which no sentence is quoted: steatosis (9 papers); Obesity (5); breast carcinoma (2); cholestasis (2); colon carcinoma (2); colorectal cancer (2); diabetes (2); fibrosis (2); Insulin resistance (2); adenocarcinoma (1); adenosquamous carcinoma (1); Anxiety (1); clear cell renal cell carcinoma (1); colitis (1); colon adenoma (1); colorectal (1); colorectal adenocarcinoma (1); Colorectal Tumors (1); Constipation (1); depression (1); esophageal squamous cell carcinoma (1); Hyperinsulinemia (1); Hypoinsulinemia (1); inflammation (1); intrahepatic cholestasis (1); leukemia (1); lipid metabolism disorders (1); lung adenocarcinoma (1); lymph node metastasis (1); lymphedema (1).
A further 10 diseases each share a sentence with SLC27A5 in 1 paper.